IL1B (interleukin 1 beta)
Diseases named in the same sentence as IL1B in open-access papers (continued):
Sharing a sentence is not in itself a finding about the gene and the disease.
infection (continued). "While there was a slight increase in IL-15 secretion (5 ± 2 vs. 8 ± 3 pg/mL) and IL-10 (1.4 ± 2.0 vs. 2.3 ± 2.5 pg/mL) upon infection, IL-8 and IL-1β remained unchanged." (PMID 41239423, 2025). "During wound healing, M1 macrophages (pro-inflammatory) dominate the early phase, producing cytokines like TNF-α and IL-1β to combat infection and clear debris." (PMID 40894219, 2025). "Several studies have shown that TLR2 and TLR4 recognize components of the fungal wall and contribute to the production of proinflammatory cytokines, such as TNF-α, IL-6, and IL-1β, which promote the recruitment of immune cells to the infection site." (PMID 41590416, 2025). "Consistent with the bone measurement results, indole supplementation during ΔtnaA infection significantly elevated IL-1β, IL-6, and TNF-α levels in the gingival tissue of the Mutant + Indole group compared to the Mutant group." (PMID 40011497, 2025). "IL-1β possesses multiple and diverse properties in response to infection, injury, and immune challenges." (PMID 40568580, 2025). "IL-1β, as a potent pro-inflammatory, is essential for the host defense response to infection, which is involved in the host response to a wide range of antigens and promotes the expression of inflammatory factors." (PMID 40005874, 2025). "It appears to be due to an interaction of phosphoinositide 3-kinase (PI3K), MAPK and NF-κB pathways, resulting in synergistic activity of the AMP and il-1β to recruit monocytes and macrophages to the site of infection." (PMID 40391212, 2025). "IL-1β, a cytokine belonging to the IL-1 family, plays a crucial role in the host’s defense against pathogens, particularly in injury and infection, and exhibits potent pro-inflammatory activity." (PMID 40573262, 2025). "NMN treatment can reduce NF-κB signaling pathway activation in bone marrow-derived macrophages (BMDM) after hvKP infection, as well as the transcription of Il6, Il1b, Tnf, and Cxcl2." (PMID 40742124, 2025). "The expression levels of IL-6 and IL-1β in the mouse serum were assessed at 12, 24, and 48 h post-infection." (PMID 40230687, 2025). "While in WT mice most cytokines measured by ELISA were increased 24 h post SARS-CoV-2 P21 infection compared to mock WT animals, Il-1β–/– and Il-1r–/– mice only differed in levels of IL-22 at this early time point." (PMID 40016339, 2025). "In SCAT of aged mice, infection induced an increase in Il10 levels at 4 and 7 dpi, Tnfa at 4 dpi, and both Il1b and Il6 at 7 dpi." (PMID 41145556, 2025). "IL-1β coordinates fish responses to infections by activating lymphocytes and inducing the release of other cytokines." (PMID 40815442, 2025). "Macrophage-derived IL-1β and IL-18 play pivotal roles in recruiting other immune cells, particularly adaptive ones, to the sites of infection." (PMID 41208996, 2025). "On the contrary, IL1β secretion is essential for host cell control of the infection, as IL1R knockout mice are more susceptible to infection." (PMID 41204030, 2025). "At day 6 post-infection, miRNAs such as miR-132, miR-15, miR-203, and miR-19 are shown to interact with central signaling molecules like NF-κB, IL-1β, VEGF, and ERK1/2." (PMID 41157560, 2025). "Although transcription of IL-1α, IL-1β, IL-6, and IL-15 genes was substantially upregulated, overall cytokine responses to infection with VR-2332 were insignificant." (PMID 40302751, 2025). "In vivo infections resulted in a consistent elevation of IL-1β induced by EIAV vaccine or by virulent strain, with much lower trajectory induced by vaccine." (PMID 40522989, 2025). "TNF- α and IL-1β contribute to the generation of protective immunity against infection with H. capsulatum." (PMID 40558960, 2025). "Activation of the inflammasome signaling pathway promotes elevated production of proinflammatory cytokines, such as IL1β, which contributes to host cell immunity during infection." (PMID 41287823, 2025).
infection (continued). "TLR2 recognizes phospholipomannans, which leads to the local production of proinflammatory cytokines such as IL-1β and IL-6, which are key mediators of immune cell recruitment to the site of infection." (PMID 41295183, 2025). "ST74 induced significantly less host cell death during the early to mid-stage of macrophage infection, supported by limited processing and release of IL-1β at 9 hpi." (PMID 40560760, 2025). "The IL-1β and iNOS levels produced by AM were also increased after infection with Mtb but decreased in the lungs of auranofin treated mice as compared to controls." (PMID 40602278, 2025). "Following infection, these cells release chemokines like IL-1β and IL-10, which promote the differentiation of naive CD4+ T cells towards the Th17 lineage while suppressing the differentiation and function of Treg cells." (PMID 41425878, 2025). "Apoptotic markers (caspase-3, Bax, Bcl-2) were analyzed by immunofluorescence and immune genes expression kinetics (TLR3/7, RIGI, MDA5, IL-1β, IL-6, TNFα, IL-10, IFNβ and β-catenin) were measured at defined time points post-infection by RT-qPCR." (PMID 41157617, 2025). "IL‐1β content increased significantly in all regions of mouse brain tissue after infection, with peaks on 3 and 4 dpi, which were particularly evident in the hippocampus." (PMID 40985474, 2025). "The production of key cytokines (IL‐1β, IL‐18, IL‐6, IL‐10, IL‐12) and nitric oxide (NO) was quantified at 24 to 96 h post‐infection." (PMID 40940710, 2025). "In comparison to the vehicle group, during the early phase of infection (4 dpi), serum levels of IL-1β (P < 0.0001) and lung tissue levels of IL-1β (P < 0.05) exhibited approximately a twofold increase, while lung tissue levels of IL-6 also doubled (P < 0.01)." (PMID 40475788, 2025). "Proinflammatory cytokines, such as TNFα, IL-1β, and IL-6, produced after pathogen infection or tissue damage, contribute to mounting an effective immune response." (PMID 40462232, 2025). "The results showed that there was an increase in TNF-α, IL-1β, and IL-10 production 24h after the infection by M. smegmatis (MOI 1:1) compared to the control group." (PMID 40142455, 2025). "IL-1β, a member of the IL-1 cytokine family, is primarily produced by monocytes and macrophages and plays a crucial role in the host defense against infection and injury." (PMID 40270542, 2025). "During infection of macrophages by C. albicans, pro-IL-1β transcription is regulated through both TLR2/MyD88 and CLR/Dectin-1/SYK pathways, activating the downstream CARD9/BCL10/MALT1 complex that is essential for IL-1β secretion." (PMID 41249509, 2025). "PCN033 infection elevated IL-1β and TNF-α levels in serum, lungs, spleens and brains while reducing TGF-β in serum, lungs, and spleens." (PMID 41295668, 2025). "An earlier study revealed that Nlrp6−/− mice produced similar levels of IL-1β following infection with S. Typhimurium, Listeria monocytogenes, and E. coli as wild-type mice did." (PMID 41062723, 2025). "We observed, herein, elevated levels of a potent pro-inflammatory cytokine, IL-1β, following infection with E. papillata." (PMID 40313946, 2025). "For example, IL-1β upregulation was observed in rainbow trout larvae as early as 3 h after Ich infection (P2)." (PMID 40509043, 2025). "The expression of some genes such as Il1b increased significantly in the early stages of infection (3–12 hpi) and the degree of gene expression upregulation decreased in the later stages (24–48 hpi)." (PMID 38992966, 2025). "In BAL at 5 weeks from infection, the same group displayed elevated levels of the pro-inflammatory cytokine IL-1β, and the matrix metalloproteinase-1 (MMP1), which remodels tissues." (PMID 41006234, 2025). "Results showed significant upregulation of TNF-α, IL-1β, IL-6, and IL-8 mRNA levels in Vero E6 cells post-infection." (PMID 40703674, 2025).
infection (continued). "To further investigate the inflammatory response, we examined plasma levels of IL-1β, IL-6, and TNFα in mice following infection with either wild-type or ΔmsbB ST." (PMID 41304196, 2025). "After the challenge, a shift in the correlation profile was observed, with a significant positive correlation between the TNFα and IL1β, indicating the potential modulation of the immune response during infection." (PMID 41150396, 2025). "TNF-α, IL-6, IL-8, and IL-1β showed higher levels in prolonged infection of HAO with rHPh-TX H5N1-Venus vs. pH1N1-mCherry." (PMID 40712003, 2025). "Initially, the immune response focused on combating the infection, evidenced by strong correlations among inflammatory cytokines like IL-1β, IL-6, IL-8, TNFα, and IFNγ." (PMID 40557167, 2025). "In this model, TNF-α signaling was the most important upstream master regulator, because its blockade completely protected mice from lethal infection and suppressed the induction of most cytokines such as IL-1β, IL-17A, IL-6, and IL-12p70." (PMID 40127923, 2025). "Among these macrophages, the percentages of NLRP3 and IL1β positive cells were significantly higher during HN878‐infection, compared with CDC1551 infection." (PMID 41287823, 2025). "Our data revealed that the levels of most inflammatory cytokines, such as IL-8, IL-1β, IL-4, IL-6, and IL-2, etc., persistently increased with time during CV-A10 infection." (PMID 41165313, 2025). "It was also demonstrated that IL-1β production during early infection was dependent on caspase-1, whereas during chronic infection, IL-1β generation was dependent on NE." (PMID 40791588, 2025). "The upregulation of IL-1β in inflammatory conditions, such as cancer and infection, is conserved in both human and murine neutrophils." (PMID 41087719, 2025). "This cascade increased the secretion of TNF-α and IL-1β compared with the untreated C. albicans-infection group." (PMID 41031111, 2025). "The level of IL-1β production induced by NcGRA7KO infection was significantly lower than that induced by infection with the parental strain Nc1 or other knockout lines." (PMID 41357231, 2025). "Colchicine, a microtubule inhibitor that is utilized in the treatment of gout, obstructs inflammasome assembly and reduces IL-1β levels in inflammation driven by infections." (PMID 41304803, 2025). "IL-1β is a central mediator of inflammation and the immune response, playing critical roles in defending the body against infections, initiating repair processes, and maintaining homeostasis." (PMID 39859545, 2025). "It is important to clarify that IL-1B is a pro-inflammatory cytokine primarily secreted by immune cells during infection or inflammatory responses." (PMID 41354698, 2025). "Activated caspase-1 cleaves pro-IL-1β into mature IL-1β, triggering local inflammatory responses to recruit immune cells for infection clearance." (PMID 41012139, 2025). "Following infection, female mice exhibited significant increases in the proinflammatory genes IL1B, IL6, and TNFA." (PMID 40143355, 2025). "IL-1β is produced in conditions such as infection or tissue damage and triggers the production of various proinflammatory cytokines, including hypotension, fever, and IL-6." (PMID 40149596, 2025). "Mean concentration values [pg/mL] ± standard deviation of selected proinflammatory cytokines: TNF-alpha, IL-1β and IL-6 in infections with atypical pathogens in patients with PCOS." (PMID 40647668, 2025). "Quantitative PCR was performed to assess the expression levels of Tnf-α, Il-1β, and Il-18 in liver and spleen tissues at 7, 14, and 21 days post-infection." (PMID 40892762, 2025). "Previous studies have revealed that K. pneumoniae is capable of inducing a pro-inflammatory cytokine response in BMECs, as evidenced by the release of cytokines such as TNF-α, IL-1β, and IL-6, consistent with our results in a model of BMECs infection." (PMID 41206543, 2025).
infection (continued). "Conversely, Pad2−/− mice showed a downregulation of M1‐related genes (Il1a, Il1b, Tnf, Cxcl2, Ccl4, Il12a, Cxcl1, Il6) compared to WT mice after PA infection." (PMID 40087815, 2025). "LF82 infection of confluent T84 cells significantly increased the release of IL-1β, IL-8, and TNF-α." (PMID 41163391, 2025). "We found that infection with ΔHla induced significantly less IL-1β than infection with USA300, likely because there were fewer neutrophils and monocytes." (PMID 41415470, 2025). "Early in the infection, corneal epithelial and resident immune cells rapidly release pro-inflammatory cytokines, such as IL-1β, TNF-α, and IFN-γ, increasing vascular permeability and recruiting additional immune cells to the site." (PMID 39861857, 2025). "Cell culture supernatants were collected for an ELISA assay to determine the secreted IL-1β protein levels 16 hr post infection (K)." (PMID 39998486, 2025). "We found that 2.5 mg/kg M3 treatment greatly reduced proinflammatory cytokine (IL6, IFNγ, TNFα, and IL-1β) mRNA expression in the lung 3 days after infection, which explains the high efficacy of M3 in protecting mice from lethal IAV infection." (PMID 39601535, 2025). "Composed of the sensor protein NLRP3, the adaptor protein ASC, and pro-caspase-1, it recognizes cellular damage and infections, triggering the release of pro-inflammatory cytokines like IL-1β and IL-18, and inducing pyroptosis." (PMID 40688353, 2025). "For instance, pro-inflammatory mediators interleukin-1 beta (IL-1β) and TNF-α induce the recruitment of accessory immune cells, eosinophils, and neutrophils to infection- or injury-susceptible areas for antimicrobial defense." (PMID 40948785, 2025). "In IPEC-J2 cells, miR-215 overexpression during infection significantly reduced the IL1β and CASP1 gene expression (p < 0.01 and p < 0.05, respectively)." (PMID 39943201, 2025). "IL-1β is promptly produced in response to infections, and decreased production of IL-1β was found to alleviate the P. aeruginosa-induced lung tissue damage and reduce the mortality of mice." (PMID 40143103, 2025). "Our results also showed that E. coli XH197291 infection elevated IL-1β and TNF-α levels in the duodenum and ileum of Zi geese." (PMID 40963585, 2025). "We detected the expression of major inflammasome genes (NLRP3, caspase-1, IL-1β, IL-18) during infection progression." (PMID 40906404, 2025). "Analysis of macrophage‐related cytokines and chemokines found that Tnf, Il1b, Il1a, Ilrn, Il17ra, Cxcl1, Cxcl2, Ccrl2, Ccl3, Ccl4, and Ccl9 expression significantly increased over the course of infection." (PMID 41117166, 2025). "Gene expression of il-1β was minimal until 14 days post-infection, followed by a significant increase at 21 days, reaching approximately 10-fold over baseline (p < 0.05)." (PMID 40607404, 2025). "Although previous studies have characterized the transcription of SAA, IL-1β, and IL-6 during Ich infection, their kinetics throughout the complete infection–recovery continuum remain uncharacterized." (PMID 40509043, 2025). "We found that the gene expression of abf-2, ape-1, Cep-1, lys-7 and Tir-1 were significantly decreased after infection with IL-1β-stimulated CFT073 compared to unstimulated CFT073." (PMID 41162597, 2025). "Since IL-1β maturation often company with pyroptosis, which is a lytic cell death induced by pathogen infection or endogenous challenge, we also observed the effects of silencing or overexpressing lncOlfr29 on the pyroptosis." (PMID 40933997, 2025). "In this study, we observed that interleukins were broadly modulated during infection, with il-1β showing robust upregulation in both stomach and intestinal tissues, particularly in the fin clipped groups." (PMID 40766313, 2025). "The results show that the expression levels of il-1β and tnf-α were significantly reduced in cells overexpressing gpx4 prior to infection with A. hydrophila." (PMID 40699725, 2025).
infection (continued). "Mmp3 and Cox2 expression were increased in IL‐1β‐treated chondrocytes with Ad‐Zmiz1 infection, compared to the corresponding non‐infected chondrocytes." (PMID 40040621, 2025). "L4 and, to a lesser extent, L3 induced a significantly higher secretion of IL-1β on day 1 post-infection (median scaled responses 1.54 [L4] and 1.31 [L3] vs. 0.55 [L1], 0.94 [L2], and 0.89 [L5]) (left)." (PMID 40162896, 2025). "At 120 min post-infection, levels of IL-1β were significantly higher in cells infected with SP1450 compared to SP1380 (82.7% and 62.7% of the nigericin control, respectively)." (PMID 39688411, 2025). "Supernatants were collected 24 hrs after infection and levels of four pro-inflammatory cytokines (TNF-α, IL-1β, IL-8, and IL-6) associated with infection were assessed." (PMID 41550953, 2025). "The IL-1β is one of the earliest expressed pro-inflammatory cytokines and enables organisms to respond promptly to infection by inducing a cascade of reactions leading to inflammation." (PMID 40018274, 2025). "During human rhinovirus (hRV) infection, inflammasome-mediated IL-1β secretion and pyroptosis in nasal epithelial progenitor cells and nasal epithelial cells depend on the DDX33/ DDX58- NLRP3- caspase-1- GSDMD axis." (PMID 39994107, 2025). "To assess ZIKV’s ability to drive monocyte inflammatory responses, we measured IL1β production in bone marrow-derived macrophages (BMDMs) following infection." (PMID 40688087, 2025). "The increased interferon and inflammatory module expression in Th17 cells and BECs also correlated with increased measured levels of IFN-α, CCL4, and IL-1β following infection." (PMID 41332562, 2025). "Studies with chronic diseases have revealed that well-balanced IL-1β and IL-17 levels are constitutively produced to sustain inflammation due to infection in the long term." (PMID 38602383, 2025). "Gene expression of pro-inflammatory cytokines IL-1β, IL-2, IL-4, and IL-6, as well as IFNγ was significantly upregulated in nasal turbinates in response to infection with all VOCs, compared to mock-infected hamster tissues." (PMID 40295859, 2025). "While only ASC-/- and GSDMD-/- mice exhibited a slight reduction in lung IL-1β expression during SARS-CoV-2 infection, the infection of IL-1β-/- mice resulted in reduced lung viral burden, pathology, and weight loss." (PMID 41011440, 2025). "IL-1β is an important component of a series of inflammatory cascades along with TNF-α in response to infection produced by various cells." (PMID 39941110, 2025). "At both 24 and 96 h post‐infection, levels of IL‐1β, IL‐18, and IL‐12 were significantly higher in the Y‐infected group compared to all other groups." (PMID 40940710, 2025). "A similar synergy in COX-2 upregulation was observed upon GF infection with oral pathogens in the presence of IL-1α, IL-1β, and interferon-α (IFN-α)." (PMID 40178270, 2025). "As expected, pro-inflammatory cytokines like IL-6, IL-1β, and TNFα were upregulated during infection, while TNFα was higher in SCFM2-Scnn1b-Tg infected mice than SCFM2-C57BL/6 infected mice." (PMID 40512037, 2025). "Cell culture supernatants were collected for an ELISA assay to determine the secreted IL-1β protein levels 16 hr post infection (E)." (PMID 39998486, 2025). "The tissue model mounted a strong inflammatory response to STm infection, as evidenced by the secretion of IL‐1β and TNF, while the anti‐inflammatory cytokine IL‐10 was also detected." (PMID 39807570, 2025). "Specifically, an autochthonous Sicilian breed, Modicana, had high levels of IL-1β, one of the most relevant cytokines involved in the control of this and other infections." (PMID 40302747, 2025). "In the case of cytokines, their relationship with infection is more unequivocally established, and IL‐1β, IL‐18, MIG, and IP‐10 have been related to COVID‐19." (PMID 39800769, 2025). "In K18-hACE2 mice, NLRP3 inflammasome activation and IL-1β release are observed late in infection (7 dpi), coinciding with fatal disease progression." (PMID 40016339, 2025).